ERG (ETS transcription factor ERG)
Diseases named in the same sentence as ERG in open-access papers (continued):
Sharing a sentence is not in itself a finding about the gene and the disease.
cancer (continued). "Strong ROCK1 staining was found in 3% of AR-negative, but in 27% of strongly AR positive cancers, in 13% of ERG-negative but in 25% of ERG positive cancers, and in 12% of PTEN normal but in 26% of PTEN deleted cancers." (PMID 31557128, 2019). "For example, the group of SNW1 negative cancers – the best prognostic group – contained 1182 cancers in ERG negative, but only 164 cancers in ERG positive cancers." (PMID 31043167, 2019). "Our data identify SNW1 expression as an ERG-dependent feature being clearly more prominent in ERG positive than in ERG negative cancers." (PMID 31043167, 2019). "PTPN12 staining was seen in 86.4% of TMPRSS2:ERG fusion positive but in only 58.4% of ERG negative cancers." (PMID 31606028, 2019). "There was a strong positive association between AR expression and ROCK1 expression in all cancers as well as in subsets of ERG negative and ERG positive cancers." (PMID 31557128, 2019). "MAPT staining was seen in 15.2 and 16% of cancers with TMPRSS2:ERG fusion detected by immunohistochemistry and fluorescence in-situ hybridization, but in only 3.5 and 3.9% of cancers without ERG staining or ERG rearrangements." (PMID 30823906, 2019). "In earlier studies we had described several molecular features that were either prognostic in ERG positive (for example, SOX9, and SENP1 or in ERG negative cancers (for example, GGH and NBS1) but not in both groups." (PMID 31043167, 2019). "For example, moderate or strong nuclear ELAC2 staining was seen in 48.1% of cancers with TMPRSS2:ERG fusion detected by FISH but in only 31.6% of cancers without such rearrangement (p< 0.0001)." (PMID 31452838, 2019). "The difference in 1-, 5- and 10-year recurrence-free survival between strong and weak nuclear ELAC2 intensity is 7.2/13.8/17.6% in all cancers, 7.4/16.1/26.5% in the ERG negative subset, and 3.1/5.7/9.8% in the ERG positive subset." (PMID 31452838, 2019). "For example, GSK3ß staining was seen in 44.5% of ERG-IHC negative but in 78.3% of ERG-IHC positive cancers." (PMID 30899444, 2019). "This was underscored by the observed significant difference in ERG expression between the fusion positive and negative cancer samples." (PMID 31537872, 2019). "This was particularly evident for the relationship with PSA recurrence, which was striking in ERG negative (p < 0.0001) but much less strong in ERG positive cancers (p = 0.0055)." (PMID 31606028, 2019). "Subgroup analyses of ERG negative (p < 0.0001) and ERG positive cancers (p = 0.0002) revealed that the prognostic impact of SNW1 was significant in both subsets." (PMID 31043167, 2019). "Most of these associations held also true in subset analyses of ERG negative or ERG positive cancers." (PMID 31557128, 2019). "Multivariate analysis revealed that the prognostic impact was independent of established prognostic features in ERG negative p<0.001) but not in ERG positive cancers." (PMID 31903168, 2019). "To estimate the impact of the Gleason grade on the prognostic power of SNW1, we performed further subset analyses in ERG negative cancers with identical classical and quantitative Gleason grade." (PMID 31043167, 2019). "Data on both ERG FISH and IHC were available from 6778 cancer samples and an identical result (ERG IHC positive and break by FISH or ERG IHC negative and missing break by FISH) was found in more than 95% of the examined cancer samples." (PMID 31043167, 2019). "Our data demonstrate strikingly higher MAPT expression levels in ERG positive than in ERG negative cancers." (PMID 30823906, 2019). "Loss of ZIC2 expression was associated with adverse outcome and correlated with significantly shorter time to biochemical recurrence in all cancers, independent of ERG and PTEN." (PMID 31640781, 2019). "PTPN12 immunostaining was seen in 86.4% of ERG IHC positive and in only 58.4% of ERG IHC negative cancers (p < 0.0001)." (PMID 31606028, 2019).
cancer (continued). "These analyses identified PTPN12 as an independent prognostic feature in all 4 scenarios, if the entire cohort or the subgroup of ERG negative cancers was considered (p < 0.0005 each)." (PMID 31606028, 2019). "The in 1-, 5- and 10-year recurrence-free survival differed between strong and weak nuclear ELAC2 intensity levels by 7.2 /13.8/17.6% in all cancers, 7.4/16.1/26.5% in the ERG negative subset and 3.1/5.7/9.8% in the ERG positive subset." (PMID 31452838, 2019). "For example, moderate to strong SNW1 staining was seen in 37.9% of ERG-IHC negative but in 71.4% of ERG-IHC positive cancers (p < 0.0001)." (PMID 31043167, 2019). "This was particularly evident in the subgroup of ERG negative cancers where this difference was statistically significant for 9 of 12 deletions (p < 0.0005 each)." (PMID 31606028, 2019). "For example, moderate to strong ROCK1 staining was seen in 63% of ERG IHC negative, but in 82% of ERG IHC positive cancers." (PMID 31557128, 2019). "Our data identify PTPN12 protein as another protein whose expression was increased in ERG positive compared to ERG negative cancers." (PMID 31606028, 2019). "Subset analyses discovered that all associations with unfavorable phenotype and prognosis were markedly stronger in ERG positive than in ERG negative cancers but still retained in the latter group." (PMID 31606028, 2019). "To better understand the prognostic power of BCAR1, we performed further subset analysis in cancers with identical classical and quantitative Gleason score in all patients and the ERG negative subset." (PMID 29304771, 2018). "Here, the Ki67 labeling index (Li) ranged from 1.5% (in BCAR1 negative cancer) to 4.0% (in strongly BCAR1 positive cancer, p < 0.0001), while this association was weaker (2.2% in BCAR1 negative vs. 3.2% in BCAR1 strong, p < 0.0001) in ERG-positive cancer." (PMID 29304771, 2018). "Strong versus negative BCAR1 expression was associated with early PSA recurrence in all tumors and was limited in subgroup analyses to the subset of ERG-negative cancer." (PMID 29304771, 2018). "Although mutations in ERG have not been reported in previous AML studies, 222 different mutations affecting 211 patients in other cancers (n = 22) such as breast, brain or soft tissue have been described." (PMID 30303964, 2018). "As in the finasteride arm, the 90-day change in PCA3 and T2:ERG did not predict cancer status (AUC ~50%, p = 0.55 and p = 0.46, respectively)." (PMID 30300367, 2018). "Thirdly, in the long-term phase of the longitudinal study, high FOXP2 levels were found to correlate with relapse frequency of ERG-negative cancers." (PMID 29725501, 2018). "Immunohistochemical staining indicated that nuclear and cytoplasmic expression of NONO, ERG, and Ets-1 was obviously detected in cancer cells, while their negative or weak expression was noted in normal and precancerous gastric mucosa." (PMID 29773901, 2018). "The association between BCAR1 expression and lymph node metastasis was puzzling because it was in the opposite direction between the ERG negative and positive cancers and significant in both subsets." (PMID 29304771, 2018). "It appears possible that different tests need to be developed for ERG-positive and ERG-negative cancer." (PMID 29304771, 2018). "Here, we additionally show that ERG and FLI1 expression is also downregulated in cancer pathology." (PMID 30500808, 2018). "This association held also true with high significance (p < 0.0001) in most subgroups of cancers with identical Gleason grade (≤ 3 + 3; 3 + 4; 4 + 3; ≥ 4 + 4;), and was independent of the ERG status (p < 0.0001), or presence of PTEN deletions (p = 0.0002)." (PMID 28415558, 2017). "Four different types of multivariate analyses were performed evaluating the clinical relevance of nuclear YB-1 accumulation in different scenarios in the subset of ERG-negative cancers." (PMID 28515422, 2017).
cancer (continued). "This held true also in the subset of ERG-negative and ERG-positive cancers (p < 0.0001; data not shown)." (PMID 28747165, 2017). "The striking limitation of the prognostic relevance of YB-1 to the subset of ERG-negative cancers raises the issue of “subtype specific” prognostic tests." (PMID 28515422, 2017). "Deletions of PTEN, 16q, and 3p13 are tightly linked to ERG expression while deletions of 6q15 and 5q21 is largely restricted to ERG-negative cancers." (PMID 27880722, 2017). "All associations between 8p deletions and clinico-pathological variables held also true in the subsets of 3,569 ERG-negative (P < 0.0001) and 2,993 ERG-positive cancers (P ≤ 0.0005)." (PMID 27880722, 2017). "It appears probable that different tests need to be developed for molecular subtypes such as for example ERG positive and ERG negative cancers." (PMID 28146062, 2017). "To better understand the prognostic power of nuclear YB-1 accumulation in ERG-negative cancers, we performed further subset analyses in cancers with identical classical and quantitative Gleason scores." (PMID 28515422, 2017). "Subset analyses revealed a similar 10-year PSA recurrence-free survival of 62% for high GGH expression in ERG negative and positive cancers." (PMID 28146062, 2017). "YB-1 protein was more abundant in ERG positive (95.1%) than in ERG negative cancers (80.4%; p < 0.0001), but any prognostic impact of YB-1 staining was limited to the ERG-negative subset." (PMID 28515422, 2017). "This held also true for the subgroups of ERG-negative (p< 0.0001) and ERG-positive (p< 0.0001) cancers." (PMID 28747165, 2017). "Data on both ERG FISH and IHC were available from 3,823 cancers with evaluable YB-1 staining, and an identical result (ERG IHC negative and missing break by FISH or ERG IHC positive and break by FISH) was found in 96% and 95.6% of the examined cancers." (PMID 28515422, 2017). "Nuclear YB-1 expression provided significant independent prognostic value beyond the established parameters in all scenarios if the analysis was limited to ERG-negative cancers." (PMID 28515422, 2017). "The association between deletions and ERCC1 expression was less clear in ERG positive than in ERG-negative cancers, which is likely due to the (already) markedly elevated levels of ERCC1 in ERG-positive tumors." (PMID 28747165, 2017). "Our “in silico” functional analysis further identified a striking association of FAM13C positivity with multiple chromosomal deletions, particularly in ERG negative cancers." (PMID 28415558, 2017). "It is also possible, that the generally higher YB-1 expression levels in ERG-positive than in ERG-negative cancers makes it more difficult to see further differences in expression with the selected experimental conditions." (PMID 28515422, 2017). "For example, positive cytoplasmic YB-1 staining was seen in 80.4% (including 27% cases with nuclear co-staining) of ERG-IHC negative but in 95.1% (34.2% nuclear co-staining) of ERG-IHC positive cancers (p ≤ 0.05 each)." (PMID 28515422, 2017). "In several of these, a prognostic impact was only seen for ERG-negative, but not for ERG-positive cancers." (PMID 28146062, 2017). "This was particularly evident for ERG negative carcinomas and only marginally visible in ERG positive carcinomas." (PMID 28747165, 2017). "ERG fusions further occur in about 50 % of initially ERG negative cancer foci during cancer progression." (PMID 27530104, 2016). "Among 59 cancer foci with ≤3 mm, 19 (32.2 %) were homogeneously ERG positive, 39 66.1 %) were homogeneously ERG negative, and one case (1.7 %) showed a heterogeneous ERG status." (PMID 27530104, 2016).
cancer (continued). "18q deletions were marginally more frequent in ERG-negative cancers irrespective of the method of ERG analysis (P = 0.0063 for ERG-IHC and P = 0.0516 for ERG-FISH analysis)." (PMID 27861151, 2016). "Young patients not only have a higher likelihood to develop homogeneously ERG positive cancer foci (32 %) than old patients (18 %), they also have a higher likelihood for developing ERG positive subpopulations in initially ERG negative cancers." (PMID 27530104, 2016). "Intrafocal ERG heterogeneity was found in 26 % high-grade cancers and in 19 % of low-grade tumors, but the difference was not statistically significant (p = 0.5694)." (PMID 27530104, 2016). "Deletions of 18q were slightly more frequent in ERG-fusion negative (8.2%) than in ERG-fusion positive cancers (6.4%, P = 0.0063)." (PMID 27861151, 2016). "It is of note, that our data do not show substantial differences in the 18q deletion rate between ERG-negative and ERG-positive cancers." (PMID 27861151, 2016). "None of 34 cancers revealed focal ERG positivity in a 6q15 deleted setting, while 6 of 42 cancers had a small area of 6q15 deletion in an ERG-positive background (p = 0.022)." (PMID 26684029, 2016). "In particular, deletions of PTEN and 3p13 define subgroups in ERG positive and deletions of 5q21 and 6q15 define subgroups in ERG negative cancers." (PMID 25825985, 2015). "While no unequivocal changes in the SOX9 expression levels were found in different stages of ERG-negative cancers, a gradual decrease of SOX9 paralleled progression to advanced stage, high Gleason grade, metastatic growth, and presence of PTEN deletions in ERG-positive cancers (p<0.0001 each)." (PMID 26030748, 2015). "A highly significant association between high-level HOOK3 expression and early PSA recurrence was found when all tumors were analyzed and also in the subgroup analyses for ERG negative and positive cancers (p<0.0001 each)." (PMID 26230842, 2015). "A subset of EPCATs is Androgen Receptor or ERG regulated, but for most novel transcripts their unique transcriptional regulation in cancer is still not fully resolved and poses a new challenging research question." (PMID 25686826, 2015). "In particular, deletions of PTEN and 3p13 define subgroups of ERG positive, and deletions of 5q21 and 6q15 define subgroups in ERG negative cancers." (PMID 25762627, 2015). "High VEGFR-1 staining was linked to PTEN deletions in the analysis of all tumors (p = 0.0002), but also in the subgroup of ERG negative (p = 0.0142) and ERG positive cancers (p = 0.0350)." (PMID 25894226, 2015). "Elevated HOXB13 expression levels were strongly linked to deletions of PTEN in all cancers as well as in the subsets of ERG- negative and ERG- positive cancers (p < 0.0001 each)." (PMID 25825985, 2015). "Deletions of 12p were found in 14.4% and 16.0% of ERG-negative cancers (according to ERG IHC and FISH analysis), and in 13.7% (IHC, p = 0.5626) and 16.0% (FISH, p = 0.9790) of ERG-positive cancers." (PMID 26293672, 2015). "Here HOOK3 staining was strongly correlated with deletions in PTEN (p<0.0001 for both ERG negative and positive cancers), 6q15 (both p<0.0001) and 5q21 (p<0.0001, p = 0.01 respectively) but not with 3p13 deletions (p = 0.10 and p = 0.73 respectively)." (PMID 26230842, 2015). "HOXB13 expression was seen in 63.4% (ERG IHC) and 64.1% (ERG FISH) of ERG-positive cancers but in only 44.1% and 49.9% of cancers without ERG staining and ERG rearrangement, respectively (p < 0.0001 each)." (PMID 25825985, 2015). "SENP1 largely did not provide independent prognostic information if all tumors or the subgroups of ERG positive and ERG negative cancers were interrogated." (PMID 26202067, 2015). "These associations varied when subgroup analysis was performed for ERG negative and ERG positive cancers." (PMID 26230842, 2015).
cancer (continued). "ERG and FLI1 genes are closely related members of the erythroblast transformation-specific (ETS) family of transcription factors, and studies have proved that these two TFs were usually involved in various types of cancer jointly." (PMID 26425543, 2015). "ERG activated cancers are most likely to develop deletions of PTEN or 3p13 while ERG negative cancers often acquire deletions of 6q or 5q." (PMID 25762627, 2015). "The application of multivariate models revealed that SENP1 largely lacked independent prognostic value if all tumors and the classical molecular subgroups of ERG positive and ERG negative cancers were analyzed." (PMID 26202067, 2015). "A comparative analysis of ERG positive and ERG negative cancers showed that these findings were largely similar in both groups even though somewhat more pronounced in ERG-negative cases." (PMID 25762627, 2015). "This association held also true with high significance in most subgroups of cancers with identical Gleason grade (≤3 + 3; 3 + 4; 4 + 3; ≥4 + 4), and also in the subset of ERG positive tumors lacking PTEN deletions (p = 0.0315)." (PMID 26202067, 2015). "Finding HOOK3 expression in 74% of ERG positive but in only 38% of ERG negative cancers (p<0.0001) further suggests functional interactions between these genes." (PMID 26230842, 2015). "ERG triggered the migratory potential of cancer cells by the overexpression of CXCR4 and ADAM metallopeptidase with a thrombospondin type 1 motif, 1 (ADAMTS1) as ChIP assay demonstrated direct binding of ERG to the promoter region for both CXCR4 and ADAMTS1." (PMID 24739220, 2014). "The largest group, which comprised those who had no ERG rearrangement and low Ki-67 LI, had a greater cancer-related survival when compared with the three other groups." (PMID 24516518, 2014). "Overall, ERG rearrangement was associated with pre-operative PSA values (P = 0.038) and cancer-related death (P = 0.02), but not with the age, clinical T stage, Gleason score, or Ki-67 labeling index (LI)." (PMID 24516518, 2014). "The diverse multivariate analyses suggest a possible independent prognostic impact of MTC02 immunostaining in a preoperative setting, especially in ERG negative cancers." (PMID 24261794, 2013). "A role of PTEN inactivation as a “progression event” associated with higher requirements for mitochondrial function is further supported by the observation that high mitochondrial content loses its prognostic relevance in PTEN deleted ERG negative cancers." (PMID 24261794, 2013). "We found that the CpG island was fully methylated in benign cells and ERG-negative cancer cell lines, with an average methylation ranging from 89.3% for LNCaP to 98.6% for PC-3." (PMID 23555854, 2013). "In summary, the results of our study highlight a different role of mitochondrial content in ERG fusion-positive and -negative cancers and identify “mitochondrial abundance” as a potential prognostic feature in ERG-negative cancers." (PMID 24261794, 2013). "By contrast, in ERG fusion-negative cancers, there was a noticeably large fraction (40%) of low-grade cancers harboring p27 loss." (PMID 24179503, 2013). "A number of studies have demonstrated gene expression profiles that were markedly distinctive between ERG fusion-positive and -negative cancers." (PMID 24179503, 2013). "p27 expression was also unrelated to clinical outcome in all cancers, as well as in the subsets of ERG fusion-positive and -negative cancers." (PMID 24179503, 2013). "In particular, there was no clear difference with respect to PSA recurrence between strongly p27-positive and -negative cancers, neither when tumors were jointly analyzed, nor in subsets of ERG fusion-negative and -positive cancers." (PMID 24179503, 2013). "That mitochondrial content has a different role and function in ERG positive and ERG negative cancers is further supported by our ERG-stratified analysis of disease outcome." (PMID 24261794, 2013).